STAT1 (signal transducer and activator of transcription 1)
Diseases named in the same sentence as STAT1 in open-access papers (continued):
Sharing a sentence is not in itself a finding about the gene and the disease.
tumor (continued). "Previous studies in solid tumors have demonstrated that prolonged interferon signaling allows tumors to acquire STAT1-related epigenomic/genomic changes contributing to the maintenance of resistance to immune checkpoint blockades, with a major contributor of IFNG being tumor-associated T cells." (PMID 38339304, 2024). "However, the specific regulatory effects of IFNγ and STAT1 signaling pathways in the anti-tumor immune response are still unknown." (PMID 38167862, 2024). "Consequently, we investigated the distribution of cells receiving IFN-γ in the tumor microenvironment by examining the phosphorylation of STAT1, a downstream molecule of the IFN-γ signaling, on tyrosine-701 (pSTAT1) 21 at various time points following T cell transfer." (PMID 39629126, 2024). "Interestingly, PD-1 inhibitor and QFM used alone or in combination showed significant changes in the tumor growth, thymus index, spleen index, tumor tissue necrosis and apoptosis, Trp-Kyn metabolism, and STAT1-AhR signaling axis in LLC-luc tumor-bearing C57BL/6 mice." (PMID 38882349, 2024). "Therefore, a combined targeted inhibition of STAT1, PARP9, PARP14 and/or DTX3L could increase the efficacy of currently available treatment for prostate, DLBCL and other high-risk tumour types harbouring an increased STAT1 signalling." (PMID 39189367, 2024). "Therefore, we further evaluated this phenomenon through a whole-cell tumor challenge to examine whether an intact and responsive host immune system is necessary for an antitumor response to be elicited in STAT1−/− mice." (PMID 38675812, 2024). "STAT1 is a tumor inhibitor, and its possible mechanism may be related to its subtype, STAT1β." (PMID 37762313, 2023). "Moreover, knockout of STAT1 in CRC cells resulted in significantly reduced tumor growth." (PMID 37173951, 2023). "Thus, thanks to the high sensitivity of Well-TEMP-seq, we can provide insights into the 5-AZA-CdR induced anti-tumor response of STAT1, HEYL, and PITX1 TFs activation in the early stage of treatment (e.g., in the first three days), which has not been unveiled before." (PMID 36882403, 2023). "Additionally, STAT1 plays a role in regulating the immunogenicity of tumor cells." (PMID 37561163, 2023). "Furthermore, tumor-infiltrating lymphocytes (TILs) were also increased in the positive-STAT1 group." (PMID 36982677, 2023). "Additionally, STAT1 deficiency leads to decreased production of C-X-C motif chemokine receptors (CXCL9, CXCL10, and CXCL11) in the tumor epithelium, all of which work as T-cell chemotactic factors, suggesting STAT is an important contributor to DOX’s effects on the antitumor immune response." (PMID 36831326, 2023). "According to recent studies, silvestrol, an inhibitor of the helicase activity of eukaryotic initiation factor 4A, prevents translation of the Stat1 mRNA and might therefore represent a potential therapeutic option to avoid tumor immune escape via the STAT1-PD-L1 axis." (PMID 38102680, 2023). "Finally, triple-stained CD68/phospho-STAT1/c-Maf cells should have been examined in each case, as results may have enabled evaluation of the role of infiltrating M1 and M2 within the tumor." (PMID 37280312, 2023). "Therefore, it is reasonable to speculate that ESCO2 may interact with STAT1 to inhibit and impair its tumor suppressor activity." (PMID 37968576, 2023). "Specifically, in the tumor from patient #7, genes involved in T cell activation and signaling such as PTPRC (which encodes CD45), LCP2, FYB, CD3E, and LCK, and in genes involved in immune response and interferon signaling such as STAT1, OAS2, and HLA were downregulated." (PMID 37620318, 2023). "Moreover, the activation of STAT1 has been reported to facilitate the transmission of tumor antigens and the activation of tumor immunity, which may also be the possible reason for the improvement of the immune microenvironment by DMKG and RT." (PMID 37438720, 2023).
tumor (continued). "STAT1 is an important upstream regulatory gene in type I interferon signaling pathway, and upregulation of type I interferon expression in tumors has been shown to facilitate immunostimulatory effects, which can further enhance anti-tumor effects after induction of anti-tumor immune responses." (PMID 37717087, 2023). "Additionally, while TRIM24 expression is low in tumour-infiltrating lymphocytes, its downregulation could, in turn, upregulate STAT1 anti-tumour activity." (PMID 35595823, 2022). "Increasing the concentration of IL-21 in the TME could reverse the failure of NK cells by activating the phosphoinositide 3-kinase (PI3K)-AKT-FoxO1 and signal transducer and activator of transcription 1 (STAT1) signalling pathways to improve the prognosis of advanced tumours." (PMID 36159866, 2022). "Therefore, we hypothesized that SPATA2 and CYLD are suppressing chemokine production in tumor cells by modulating NF-κB and/or STAT1 signaling." (PMID 36531014, 2022). "However, the non-canonical elevation of Casp8 expression we observed in CAL27 cells following STAT1 inhibition warrants further investigation, as this may be a driver behind tumour survival in cases of HNSCC with high expression of STAT1." (PMID 35595823, 2022). "However, the role of STAT1 expression by tumour cells and its regulation during HNSCC is unclear." (PMID 35595823, 2022). "Furthermore, deletion of PTPN1 and PTPN2 in DCs stimulated the growth of IL-12 and IFN-γ, which amplified the IL-12/STAT4/IFN-γ/STAT1/IL-12 positive autocrine loop, boosting the therapeutic potential of mature monocyte-derived dendritic cells (moDCs) in tumor-bearing mice." (PMID 35957898, 2022). "However, STAT1 was required for anti-tumour functions of T cells during HNSCC in vivo." (PMID 35595823, 2022). "Therefore, we next examined potential STAT1 mediated anti-tumour mechanisms." (PMID 35595823, 2022). "Taken together, these data confirm the biology underpinning the bulk tumour-derived HPS is significantly associated with functional STAT1 activity and APP in tumour-infiltrating professional APC in CC, which may be downstream of a dsRNA and/or viral response in a subset of HiFi tumours." (PMID 35477539, 2022). "Interestingly, Stat1 has been identified as a sex-specific tumor suppressor in CAC in mice." (PMID 36142324, 2022). "Elevation of dsRNA and viral response signalling was observed in HiFi tumours with reduced relapse rates and may provide a biological explanation for the differential activation status of this STAT1 and IFN-related biology in the different subsets of HiFi tumours." (PMID 35477539, 2022). "In addition, the activation of the NOD1 receptor induced by IE-DAP could upregulate TF STAT1, acting as an active transcription factor to boost tumor metastasis in PCa and upregulate the target gene CD3G." (PMID 35164166, 2022). "In addition, we demonstrated that the interruption of the TGF-β1-mediated PKM2/STAT1-PD-L1 axis could remodel the immune microenvironment by activating NK cells and restrain tumor growth." (PMID 34862460, 2022). "In light of the finding that PD-1/PD-L1 expression STAT1-deficient immune cells were elevated in the context of STAT1-competent tumours but not STAT1-deficient tumours, it appears that STAT1 expression by tumour cells plays a direct role in inducing immune checkpoint signalling between immune cells." (PMID 35595823, 2022). "The anti-tumor effect of DUSP26 is associated with inhibition of MAPK and Akt signaling pathways that may arise from dephosphorylation of signaling proteins including, p38, STAT1, ERK, YAP, Akt, and AMPK, which are known substrate of DUSP26 enzymatic activity." (PMID 33718185, 2021). "Signal transducer and activator of transcription 1 is an important transducer and transcript factor which exerts contradictory effects by directly regulating target genes or cooperating with other transcription factors to mediate tumor progression and drug resistance." (PMID 33834023, 2021).
tumor (continued). "Therefore, activated Stat1 might suppress miR-145 expression and further increase Oct4 expression to form a feedback loop in promoting tumor progression." (PMID 34685622, 2021). "It has been suggested that the IFN/STAT1 signaling pathway may promote the growth of tumor cells." (PMID 35003395, 2021). "In addition, there was no STAT1 phosphorylation detected, which may be due to the level of STAT1 phosphorylation in these two murine tumor cell lines." (PMID 34578339, 2021). "However, a positive tumor STAT1 expression implied a strong immune microenvironment." (PMID 34758826, 2021). "However, STAT1 can exert contrasting effects on tumor progression." (PMID 34943817, 2021). "Another study reported that STAT1 could promote tumor growth by mediating tumor immunosuppression." (PMID 34943817, 2021). "Besides, interferon triggers STAT1, so the cell releases cytokines to inhibit tumor growth." (PMID 34177892, 2021). "Furthermore, tumor infiltrating lymphocytes (TILs) were increased in the positive-STAT1 group." (PMID 34758826, 2021). "IFN/STAT1 signaling potentiates cell cycle arrest and apoptosis in tumor cells, induces angiostatic responses, increases antigen processing and presentation by tumor cells, and primes the innate and adaptive immune cells to activate immune cell subsets (Th1/CTL; NK) that promote anti-tumor immunity." (PMID 33807608, 2021). "Interestingly, the overexpression of NFκB and STAT1 could be a potential therapeutic strategy because they promote phenotypes that could balance the behavior of macrophages in a tumor microenvironment, favoring tumoricidal capacity." (PMID 34177892, 2021). "However, they also showed increased numbers of Tregs, which could be due to tumor cell-intrinsic Stat1-Ido1 expression." (PMID 32444775, 2020). "Next, we investigated whether SPHK1 reduces the tumor suppressive function of STAT1." (PMID 32260399, 2020). "The impact of STAT1 isoforms on tumor surveillance is unknown." (PMID 33042133, 2020). "As ICB induced a similar immune infiltrate in RT2-cancers and in Stat1- and Cdkn2a-deficient RT2-cancers, the data strongly suggest that senescence induction in the cancer cells was a prerequisite for tumour cell clearance by TH1 cells and IFN-γ-activated type I macrophages." (PMID 32165639, 2020). "Our previous study showed that STAT1 may have a tumor suppressive role in MB." (PMID 32992699, 2020). "However, Stat1∆IECApcMin tumors displayed a significant upregulation of STAT1 in the tumor stroma." (PMID 32444775, 2020). "The results from this study indicate that STAT1 may contribute to miR-29-mediated tumor inhibition." (PMID 31382461, 2019). "Heterogeneity in the tumor might also affect the cellular response to IFN/STAT1." (PMID 30709063, 2019). "Consequently, the anti-tumor effect of p-STAT1 is attenuated by the pro-tumor effect of u-STAT1." (PMID 30456450, 2019). "Interestingly, this study found that male STAT1-DIEC mice were significantly more susceptible than their female counterparts, suggesting that, in epithelial compartments, the tumour suppressor function of STAT1 may be influenced by gender." (PMID 30538296, 2019). "Therefore, it is possible that the addition of IL-27 alongside STAT3 inhibitors may serve to further enhance their efficacy, as inhibition of STAT3 could favor STAT1-dominant signaling, promoting the anti-tumor capacity of IL-27." (PMID 31681561, 2019). "Thus, CD4+ and CD8+ T cells frequently infiltrate GBC tumor tissues, may lead to IFNγ stimulation of tumor cells and thereby, to activation of tumor suppressive STAT1 signaling." (PMID 30886199, 2019). "To investigate whether the deletion of STAT1 results in compensatory accumulation of monocytes and granulocytes, as well as in promoting inflammation and tumor growth in STAT1−/− AOM/DSS mice, we evaluated the expression of CD11b, Ly6C, and Ly6G in the spleens and peripheral blood." (PMID 30235866, 2018). "In nu61 tumour, STAT1 might lead to radioresistance by impairing apoptotic." (PMID 29492196, 2018).
tumor (continued). "While STAT3 is an oncogene, STAT1 may function as a tumor suppressor." (PMID 29854771, 2018). "However, the effects of IL21 on angiogenesis are complicated: in a tumor environment with abundant growth IL-21R activation was shown to be angiostatic, and IL-21 administration decreased tumor vascular density and tumor size in mice bearing EG7 tumor cells via STAT1 activation." (PMID 29358309, 2018). "IFN-γ, thus, may inhibit tumor cell growth through a STAT1-dependent pathway." (PMID 30235866, 2018). "Therefore, the Stat1-null tumor cell line SSM2 was used to study macrophage migration." (PMID 28865492, 2017). "However, our data here show that these drugs also bind STATs that are associated with Th1 immune responses and therefore may contribute to anti-tumor immunity, such as STAT1." (PMID 28903353, 2017). "The maximum tolerated chemotherapy enhanced STAT-1 and NF-κB activity in carcinoma-associated fibroblasts, leading to secretion of ELR motif–positive (ELR+) chemokines, which signal through CXCR-2 on carcinoma cells to trigger them to converse to tumor-initiating cells." (PMID 28328969, 2017). "Interestingly, STAT1 has been reported to have both tumor suppressive and protumorigenic activity." (PMID 27705947, 2016). "However, cells with low STAT1 expression could have a proliferative advantage resulting in significant increase in tumor growth over the time period of 40 days." (PMID 27191495, 2016). "At the same time, the Jak-Stat1 (Janus Kinase- Signal transducers and activators of transcription 1) pathway can be stimulated by IFNα, which consequently activates effector T cells, natural killer (NK) cells, and dendritic cells, thereby indirectly enhancing the cytotoxic effect on tumor cells." (PMID 27389040, 2016). "However, RNAseq analysis of these tumor xenografts also uncovered modulation of many STAT1-regulated genes, including many, involved in radiation resistance, raising the possibility that C188-9 targeted STAT1, in addition to STAT3, in these tumors." (PMID 27027445, 2016). "Thus, STAT1 can also favour carcinogenesis and tumour survival." (PMID 25705130, 2015). "In this contest, the ability of tumour cells to express MHC II could be a consequence of p48 EBP1 activity that upregulates MHC II expression at transcriptional level via STAT1 activation and by a post-transcriptional regulation, which increases mRNAs stability." (PMID 26081906, 2015). "STAT1 is another protein shown to be regulated by STAT3 but may support or suppress tumor growth." (PMID 24743777, 2014). "Taken together, our study suggests that the combined targeted inhibition of STAT1, ARTD8, ARTD9 and/or DTX3L could increase the efficacy of chemotherapy or radiation treatment in prostate and other high-risk tumor types with an increased STAT1- and STAT3-signaling." (PMID 24886089, 2014). "In the present study, we tested our hypothesis that STAT1 is a tumor suppressor in ESCC." (PMID 25355139, 2014). "It is also important to consider a recent report that showed that doxorubicin increased HIF-1α expression in a tumour mouse model through a STAT1-nitric oxide dependent mechanism, which suggests that certain cancer cells may have a different response to doxorubicin in vivo." (PMID 24835245, 2014). "Therefore, STAT1 might exert a broader tumor suppression function against multiple oncogenic pathways." (PMID 22264274, 2012). "For this reason, it has been traditionally thought that STAT1 may function as a tumor suppressor." (PMID 22242177, 2012). "Therefore, the tumor suppression function of STAT1 is cell-autonomous." (PMID 22264274, 2012). "These JAK kinases are known to modulate multiple STAT family members, including STAT1 and STAT3.These members of the signal transducer and activator of transcription (STAT) family of transcription factors have been implicated in transformation, tumor cell survival, invasion, and metastasis." (PMID 22537161, 2012).
tumor (continued). "We have hypothesised that DNMTi can also act through the activation of the IFNγ-signalling pathway components and we therefore focused on the expression levels of the selected genes from this pathway, namely interferon responsible factors 1 (IRF-1) and 8 (IRF-8) and STAT-1 in tumour cells." (PMID 22015556, 2011). "Indeed, the gp130-family cytokine IL-27 may promote an anti-tumour response by suppressing Th17 cell polarization and favouring Th1 differentiation through its capacity to activate Stat1." (PMID 20478049, 2010). "These cells have several characteristics of tumor associated macrophages (TAMs), including impaired activation of NF-κB, lack of nitric oxide production in response to LPS/IFNγ (not shown) and high constitutive STAT1 signaling." (PMID 20661477, 2010). "Therefore, it is reasonable to propose that once tumor cells of different types acquire resistance to the IFN/STAT1 pathway and are then selected based on this resistance, they are also intrinsically resistant to a wide variety of cytotoxic and genotoxic insults." (PMID 19503789, 2009). "We hypothesized that tumor clones that constitutively overexpress this pathway are preferentially selected by the host microenvironment due to a resistance to STAT1-dependent cytotoxicity and demonstrate increased metastatic ability combined with increased resistance to genotoxic stress." (PMID 19503789, 2009). "Consequently, compounds that target Stat3 while sparing Stat1, leaving its anti-oncogenic functions unopposed, may result in a synergistic anti-tumor effect." (PMID 19274102, 2009). "In addition, these data demonstrate the ability of STAT1 to protect against IR-induced suppression of genes and proteins belonging to energy-related pathways which may protect tumour cells from energy deprivation and mediate radioresistance." (PMID 19891767, 2009). "Given that STAT1 KD tumours were also significantly radio sensitized compared to WT tumours in vivo, our results suggests that a potential mechanism of tumour radio sensitization through STAT1 suppression may be IR-induced energy deprivation of proliferating tumour cells." (PMID 19891767, 2009). "This activation leads to the elimination of the majority of the tumour cells, sensitive to Stat1-delivered cytotoxicity but also induces the selection of ‘nu61-like’ clones, which are resistant to irradiation and the stromal death ligands due to suppression of Stat1-dependent apoptotic pathways." (PMID 19437244, 2009). "Importantly, our data suggest that IR-induced up-regulation of IL6 in parental SCC61 tumour cells might be one of the initial events in the activation of the Stat1 pathway." (PMID 19437244, 2009). "Thus, we report that a previously uncharacterized role of STAT1 in regulating the expression of genes involved in energy metabolism may mediate enhanced tumour growth and radio resistance." (PMID 19891767, 2009). "The second conclusion is that the lung microenvironment significantly up-regulates the IFN/STAT1 pathway in tumor clones, which may create a selection pressure and provide a survival advantage to the preexisting STAT1H clones that are inherently resistant to this cytotoxic microenvironment." (PMID 19503789, 2009). "Although the increased tumor formation in urethane treated Stat1−/− mice could partly involve defects in tumor immunosurveillance, the higher incidence of lung tumor formation in Stat1−/− compared to Stat1+/+ mice was proportional to Ras-MAPK activation and inversely proportional to p27Kip1." (PMID 18941537, 2008). "Pharmacological inhibition of STAT1 with fludarabine abrogates WISP-1-induced M2 TAM apoptosis and reprogramming, thereby enhancing anti-tumor immunity." (PMID 41522359, 2026).